MIR6761 (microRNA 6761)
Synonyms: hsa-mir-6761
Gene: MicroRNA gene on chromosome 12 (111,799,834 to 111,799,905, forward strand). Ensembl gene ENSG00000274697.
Homologues: Orthologues: chimpanzee MIR6761 (100% identical).